RNU6-866P (RNA, U6 small nuclear 866, pseudogene)
Gene: Small nuclear RNA gene on chromosome 17 (38,755,279 to 38,755,400, reverse strand). Ensembl gene ENSG00000274607.
Homologues: Orthologues: chimpanzee U6 (99% identical). Paralogues in human: RNU6-1243P (68% identical), RNU6-694P (66% identical), RNU6-1216P (66% identical), RNU6-1083P (65% identical), RNU6-1147P (65% identical), RNU6-11P (65% identical), RNU6-140P (65% identical), RNU6-37P (65% identical), RNU6-73P (65% identical), RNU6-812P (65% identical), RNU6-944P (65% identical), RNU6-1069P (64% identical), and 1284 more.